DES (desmin)
Diseases named in the same sentence as DES in open-access papers (continued):
Sharing a sentence is not in itself a finding about the gene and the disease.
desmoplastic small round cell tumor (6 papers, 2016 to 2025). Desmoplastic small round cell tumor (DSRCT) is an aggressive soft tissue cancer that typically arises in serous lined surfaces of the abdominal or pelvic peritoneum, and spreads to the omentum, lymph nodes and hematogenously disseminates especially to the liver. "Desmoplastic small round-cell tumors (DSRCTs) possess a distinctive, diagnostically significant immunophenotype, showing coexpression of epithelial (keratin), mesenchymal (desmin, vimentin), and neural (NSE) markers." (PMID 35372059, 2022). "Osteosarcoma and desmoplastic small round cell tumors (DSRCT) have been documented to express both epithelial and mesenchymal markers, such as keratin, cadherins, desmin, and vimentin." (PMID 34063272, 2021). "Expression of desmin is reported in a few cases, and can be confused with ARMS or desmoplastic small round-cell tumor (DSRCT)." (PMID 34203801, 2021). "He underwent a CT-guided biopsy that revealed a desmoplastic small round cell tumor (DSRCT), showing positivity for EMA, desmin, and nuclear staining for WT1 (carboxy-terminus antibody)." (PMID 27863505, 2016).
pancreatic cancer (6 papers, 2009 to 2022). "With additional dual CD31‒desmin immunolabeling, we found more foci of VI than by H&E staining in the present study and dual CD31-desmin immunolabeling could more stratify for patients with surgically resected pancreatic cancers." (PMID 33253282, 2020). "In addition, although desmin (DES) is expressed in smooth muscle tissue, it has been found to be more sensitive in the detection of vascular invasion in gastric, colorectal and pancreatic cancers." (PMID 35923703, 2022).
Wilms tumor (6 papers, 2017 to 2025). An embryonal neoplasm characterized by the presence of epithelial, mesenchymal, and blastema components. "Wilms tumours are often positive for keratin, vimentin, desmin, actin, and WT1, which distinguishes this type of tumour from other malignancies." (PMID 40177273, 2025). "Nephroblastomas are generally positive for keratin, vimentin, desmin, actin, and WT1, allowing this form of tumour to be distinguished from other unusual entities." (PMID 40177273, 2025). "Although not necessary for the histopathological diagnosis, the immunoprofile of Wilms' tumor shows that blastemal cells regularly express vimentin and may also show positivity for neuron-specific enolase, desmin, and cytokeratin." (PMID 28845162, 2017). "Markers such as WT1, which is typically positive in Wilms’ tumor (in addition to PAX8, CD56, and CD57), help confirm a nephroblastic origin, while others like cytokeratins, desmin, and S-100 protein assist in identifying the specific tissue types within a tumor." (PMID 39596492, 2024). "PAN-cytokeratin and WT1, two major markers for nephroblastoma were negative as was desmin, a mesenchymal marker which can be positive in blastema-predominant nephroblastoma." (PMID 28818093, 2017). "WT1, Desmin, NSE, and cytokeratin cocktail CK22 are negative in CCSK but positive in blastema-predominant Wilms′ tumor." (PMID 31676003, 2019).
carcinosarcoma (5 papers, 2013 to 2025). A malignant tumor composed of a mixture of carcinomatous and sarcomatous elements. "The two carcinosarcomas showing heterologous skeletal muscle differentiation showed focal desmin and myogenin expression." (PMID 41202566, 2025).
cardiac conduction disease (5 papers, 2019 to 2023). "For instance, DES encodes the intermediate filament protein desmin, which is expressed in cardiac, skeletal, and smooth muscle cells, and its mutations can cause isolated cardiomyopathies and cardiac conduction diseases." (PMID 31379707, 2019).
diabetes (5 papers, 2020 to 2023). "Diabetes mellitus (DM) can cause desmin to become dysregulated, following episodes of nitrosative stress, through the activation of the iNOS/mTOR/TIMP-1 pathway, thereby stimulating collagen deposition in the myocardium." (PMID 35625721, 2022). "The DM VitDD group showed a significant increase in desmin immunostaining at 24 weeks after diabetes induction (P = 0.0004) compared to rats of the Ctrl VitDD and DM VitD groups." (PMID 37391399, 2023). "Interestingly, induction of type 1 diabetes mellitus (T1DM) in rats was reported to cause a disordered and irregular pattern of desmin arrangement in cardiomyocytes one year post DM induction." (PMID 35625721, 2022).
distal myopathies (5 papers, 2008 to 2026). "A genetic panel for distal myopathies with cardiac involvement identified the pathological desmin gene mutation DES (NM_001927.4) - c.1360C>T; (p.(Arg454Trp))." (PMID 37082475, 2023).
embryonal rhabdomyosarcoma (5 papers, 2020 to 2024). A poorly circumscribed morphologic variant of rhabdomyosarcoma. "Patient 47 was initially diagnosed with an embryonal rhabdomyosarcoma but was found in our current analyses to be immunonegative for all of the tested muscle markers including desmin, myogenin, myoglobin, and myoD1." (PMID 37395142, 2023). "The authors found cytoplasmic positivity for desmin and nuclei positivity for myogenin, in embryonal rhabdomyosarcoma, and also in one case positivity for MyoD1 (Peters S., Silva J., Morales L., Beghdad M., Bhandarkar A.,and Shahidatul-Adha M.)." (PMID 36173721, 2022). "Myogenic markers (desmin, myogenin, MyoD1) are negative, excluding the differential diagnostic consideration of embryonal rhabdomyosarcoma, which frequently also has myxoid stroma, and shows locally aggressive features on imaging." (PMID 39597961, 2024). "Cytoplasmic positive for desmin and nuclei positive for myogenin in embryonal rhabdomyosarcoma." (PMID 36173721, 2022). "The final diagnose was embryonal rhabdomyosarcoma (ERMS) with immunohistochemical staining positivity for myogenin, smooth muscle actin (EMA), desmin and myoD1." (PMID 32736545, 2020).
fibrosis (5 papers, 2019 to 2025). the formation of excess fibrous connective tissue in an organ or tissue in a reparative or reactive process. "Histological analysis further assessed the impact of desmin loss on cardiac fibrosis in mdx mice." (PMID 41163301, 2025). "Monocyte-derived macrophages in mouse livers are located in the tissue fibrosis area near desmin-positive hepatic stellate cells, thus indicating their contribution to liver fibrosis." (PMID 38115130, 2023). "HPSCs are like hepatic stellate cells, which are important effector cells in hepatic fibrosis, and stain positive for vimentin, desmin, and α-SMA." (PMID 36332889, 2022). "Treated DKI mice, however, showed an aberrant subcellular localization of desmin, unchanged functional cardiac parameters, and a trend toward an increased cardiac fibrosis." (PMID 32322014, 2019).
glioma (5 papers, 2008 to 2023). A benign or malignant brain and spinal cord tumor that arises from glial cells (astrocytes, oligodendrocytes, ependymal cells). "The correlation between CCL5 and the pericyte markers (Desmin (DES), platelet derived growth factor receptor beta (PDGFRB) or actin alpha 2 (ACTA2)) was confirmed in both the TCGA-GBM and the Chinese Glioma Genome Atlas (CGGA)-GBM datasets." (PMID 34239070, 2021). "Human MSCs have been shown to up-regulate the expression of pericyte markers desmin, αSMA, and NG2 upon the stimulation with glioma-conditioned cell culture medium, suggesting that glioma can induce the differentiation of MSCs into pericytes." (PMID 24213237, 2012). "Immunostaining control and IUE glioma mouse models with Desmin, a marker of pericyte and smooth muscle cells, revealed no change in the vascular pericyte coverage in IUE DMG tumors, which maintained the same extent of pericyte coverage as the normal brainstem." (PMID 34425907, 2021).
glomerulosclerosis (5 papers, 2014 to 2024). A hardening of the kidney glomerulus caused by scarring of the blood vessels. "Neonatally uninephrectomized male rats had more glomerulosclerosis and podocyte damage compared to females, which was assessed by a semiquantitative score and desmin staining." (PMID 37624430, 2023). "In our study, HBOT reduced glomerulosclerosis, interstitial inflammation, and fibrosis independently of FN and HIF-1α, indicating that the reduction in the intensity of fibrogenesis is related, at least partly, to the improvement in desmin protein expression." (PMID 39767695, 2024). "An increase in the desmin, vimentin and α-SMA expressions may contribute to the accumulation of ECM and consequent glomerulosclerosis and tubulointerstitial fibrosis considered the end common pathway to all progressive kidney diseases and which can culminate in ESRD." (PMID 37391399, 2023).
hemangiopericytoma (5 papers, 2016 to 2024). An antiquated term that refers to benign or malignant mesenchymal neoplasms characterized by the presence of neoplastic spindle-shaped to round cells arranged around thin-walled branching vascular spaces. "Immunohistochemical staining for vimentin and collagen type IV has also been proposed as a method to confirm hemangiopericytoma, in combination with negative stain for S-100, desmin, laminin, cytokeratins, and factor VIII-related antigen." (PMID 33204688, 2020). "The histopathologic examination and immunohistochemistry staining results (positive for CD34, CD31 and smooth muscle actin, but negative for CD99, S100, B-cell lymphoma 2 (bcl-2) and desmin) confirmed the diagnosis of hemangiopericytoma." (PMID 29785407, 2018).
ischemia (5 papers, 2012 to 2026). A hypoperfusion of the BLOOD through an organ or tissue caused by a PATHOLOGIC CONSTRICTION or obstruction of its BLOOD VESSELS, or an absence of BLOOD CIRCULATION. "In the cases of these two groups, it was noted that desmin stained weakly in terms of staining intensity and intensity in the ischemia areas seen as small foci." (PMID 40240703, 2025). "Staining of SALD and SAHD group cases with desmin antibody was consistent with histomorphologically observed early signs of acute myocardial infraction and ischemia findings." (PMID 40240703, 2025). "In myocardial ischemia, the depletion of desmin from the cytoplasm of the heart cell begins 30 min after the onset of ischemia, and within 90–120 min, depletion is complete." (PMID 39062865, 2024). "As expected, the number of blood vessels was significantly increased in the ipsilateral hemisphere in VEGF overexpression animals and desmin + staining demonstrated coverage of microvasculature by pericyte cells in the ipsilateral hemisphere after ischemia." (PMID 35175562, 2022). "Additional markers such as desmin disruption and S100A1 depletion further assist in identifying early ischemia." (PMID 41596321, 2026). "Inflammatory and immunohistochemical markers such as CRP, IL-6, fibronectin, desmin, complement C5b-9, and S100A1 contribute to the identification of early ischemia and myocarditis, particularly when routine histology is inconclusive." (PMID 41596321, 2026). "To investigate the effects of SB-3CT on gelatinase-mediated proteolysis of laminin after embolic ischemia in mice, we used triple-color confocal imaging of the well-established pericyte markers α-smooth muscle actin (α-SMA), chondroitin sulfate proteoglycan NG2, and desmin." (PMID 22587708, 2012).
muscle disorders (5 papers, 2015 to 2025). "Mutations affecting DESMIN expression or bioactivity in human cause severe muscle disorders known as desmopathies." (PMID 39147882, 2025). "Mutations in the desmin (DES) gene lead to myofibrillar myopathies, a group of muscle disorders characterized by the presence of heterogeneous desmin protein aggregates." (PMID 37176020, 2023). "Our study identifies a new protein coordinating DESMIN-mediated mitochondrial organization in skeletal muscle, which may hold the potential as a promising therapeutic target for muscle disorders." (PMID 39147882, 2025).
myofibroblastoma (5 papers, 2015 to 2023). A benign, well circumscribed soft tissue neoplasm characterized by the presence of spindle shaped myofibroblasts and mast cells in a collagenous stroma. "In our case, myofibroblastoma should be traditionally considered in the differential diagnosis because not only CD 34, but also desmin and alpha-smooth muscle actin were positive." (PMID 36550858, 2022). "The sensitivity of CD34 and desmin for detecting mammary-type myofibroblastoma is close to 90%." (PMID 30567070, 2018). "IHC stains for desmin and CD34 tested positive in 89% and 91%, respectively, in Howitt’s series of 143 patients with mammary and extra-mammary myofibroblastomas." (PMID 37232796, 2023). "This group includes two similar tumors: spindle cell lipomas and cellular angiofibromas which are differentiated from myofibroblastomas by the lack of desmin and the lack of adipocytes, respectively." (PMID 37232796, 2023). "Moreover, spindle cell lipoma does not stain for desmin, whereas mammary-type myofibroblastoma is always positive for this immunohistochemical marker." (PMID 26033228, 2015).
osteosarcoma (5 papers, 2007 to 2024). A usually aggressive malignant bone-forming mesenchymal neoplasm, predominantly affecting adolescents and young adults. "Expression levels of markers associated with human OSA including alkaline phosphatase, desmin, bone morphogenetic protein 4 and runt related transcription factor 2 were described in spontaneously arising canine osteosarcoma." (PMID 36288137, 2022). "Both osseous and extraosseous osteosarcomas show notoriously varied immunophenotypes by reacting to such reagents as factor-XIII related antigen, S100, desmin, alpha-smooth muscle actin, cytokeratin, and epithelial membrane antigen." (PMID 17504524, 2007). "Immunohistochemical myogenic markers such as SMA and desmin are important in differentiating LMSB from UPS, while focal malignant osteoid formation and negative myogenic markers help differentiate LMSB from fibroblastic osteosarcoma." (PMID 39312383, 2024). "Furthermore, we stained the osteosarcoma tumors for both the vessel marker CD31 and the pericyte marker Desmin to study the effect of vaccination on vessel functionality." (PMID 31001265, 2019).
renal cell carcinoma (5 papers, 2007 to 2024). "Immunohistochemistry indicated FLI-1(+), CD99(+), Vimentin(+), CyclinD1(+), WT-1(+), EMA(+), Bcl2(-), Ki-67(+) 60%, CD56(-), CK(-), CD34(-), Desmin(-), and SMA(-), which suggested that renal clear cell sarcoma may not rule out renal cell carcinoma." (PMID 33859949, 2021).
angiomyxoma (4 papers, 2020 to 2025). A benign soft tissue neoplasm characterized by the presence of neoplastic spindle and stellate cells, and vascular proliferation in a myxoid stroma. "Aggressive angiomyxomas display myxoid stroma, thick-walled vessels, and positivity for desmin, ER/PR, and variably CD34." (PMID 40428263, 2025). "The histopathology of these three cases revealed invasive angiomyxoma, as confirmed by immunohistochemical staining, which demonstrated positive expression of desmin, vimentin, estrogen, and progesterone receptors." (PMID 38590660, 2024).
atrioventricular block (4 papers, 2018 to 2024). A heart block that is initiated in the atrioventricular node. "Desmin was linked to ACM in 2009 with the founder variant c.38C>T (Ser13Phe) in index cases exhibiting variable phenotypes characterized by high-grade AV block, right-ventricle (RV) involvement and neurologic symptoms mainly affecting the lower limbs." (PMID 38892455, 2024).
colon cancer (4 papers, 2004 to 2017). "Desmin has also been used in a study of colon cancer as a marker for fat storing cells, and, in a study of colon polyps from 10 cases, all were negative for desmin." (PMID 16959042, 2006). "For colon cancer single gene expression, three axes for discriminating tissue types are: 1) Human monocyte-derived neutrophil-activating protein (MONAP); 2) Human desmin gene and 3) Human cysteine-rich protein (CRP) gene." (PMID 15469618, 2004). "Further analysis of the topological architectures of the network identified three known hub cancer genes (IL8; DES and ENO1), while two novel hub genes (RBM9 and RPL30) may define new central elements in the gene network specific to colon cancer." (PMID 18691435, 2008). "In two of these data sets, one or two genes had relatively high frequencies not noticeable with rules involving 20 or 50 genes: desmin for classifying colon cancer versus normal tissue; and zyxin and secretory granule proteoglycan genes for classifying two types of leukemia." (PMID 16959042, 2006).
fibromatosis (4 papers, 2009 to 2025). A poorly circumscribed neoplasm arising from the soft tissues. "Immunohistochemical studies showed the tumor cells to be positive for smooth muscle myosin, desmin, CD10, and calponin, consistent with fibromatosis." (PMID 29780440, 2018). "Speaking of IHC, the result of staining of CKs, desmin, p63, CD34, and nuclear β-catenin on IHC are all negative while CK expression is rich in lesion of fibromatosis-like MBC and BDF." (PMID 40008005, 2025).
gastric cancer (4 papers, 2022 to 2024). A primary or metastatic malignant neoplasm involving the stomach. "Lastly, colorectal and gastric cancers exhibit a shared emphasis on the genes DES, RNF150, and CHRDL1, highlighting a common gene influence pattern." (PMID 39596491, 2024). "Then, a novel TGF-β-associated prognostic model, including SRPX2, SGCE, DES, MMP7, and KRT17, was constructed, and the risk score was demonstrated as an independent prognostic factor for gastric cancer patients." (PMID 36467074, 2022). "Studies have shown that desmin (DES) protein is more advantageous than elastin protein in detecting vascular invasion in gastric cancer and is considered one of the markers of tumor invasion." (PMID 36467074, 2022). "The results of immunohistochemistry showed that the protein expression levels of RBP7, DES, SPP1, VIP, and PRKCG in gastric cancer tissues were higher than those in normal tissues, while PNOC, TNFRSF12A, and TUBB3 proteins are less expressed in gastric cancer tissues than normal tissues." (PMID 35174205, 2022).
glomus tumor (4 papers, 2016 to 2025). A rare benign or malignant mesenchymal neoplasm arising from cells that resemble the modified smooth muscle cells of the glomus body. "Our findings reinforce the characteristic IHC profile observed in glomus tumors, marked by positive staining for vimentin, SMA, actin, and desmin, which underscore the tumor's smooth muscle and mesenchymal origins." (PMID 39776317, 2025). "IHC is used for the definitive diagnosis of glomus tumors, which are known to stain positively for SMA and muscle-specific actin and stain negatively for desmin and S100." (PMID 38910613, 2024).
malignant mesothelioma (4 papers, 2016 to 2021). A malignant neoplasm of the pleura or peritoneum, arising from mesothelial cells. "A recent study demonstrated that desmin loss is observed in 92% malignant mesothelioma samples, 76% malignant effusions, 29% benign mesothelial hyperplasia tissues, but not in the reactive effusions." (PMID 31379707, 2019). "Thus, desmin may serve as a useful biomarker in the discrimination between reactive mesothelial proliferation and malignant mesothelioma." (PMID 31379707, 2019). "Malignant mesotheliomas have no characteristic paranuclear dot-like expressions of desmin and vimentin." (PMID 34193155, 2021).